CDK4 (cyclin dependent kinase 4)
Diseases named in the same sentence as CDK4 in open-access papers (continued):
Sharing a sentence is not in itself a finding about the gene and the disease.
tumor (continued). "Another 16% showed significant amplifications or increases in mRNA expression of CDK4, CDK6, and/or Cyclin D1 expression; both these classes of mutations would contribute to an aberrantly overactive cell cycle and, presumably, tumor growth." (PMID 29644000, 2018). "It has been shown that neutralization of the tumor suppressor activity of RB is usually mediated by cdk4-dependent phosphorylation at Ser78033." (PMID 30271949, 2018). "Several important cell cycle regulators were found differentially expressed in the reprogrammed tumours, including CDK4, E2F5, and CDKN1B (P27), WEE1, CDKN3." (PMID 29662623, 2018). "CDK4/6 function as the major oncogenic drivers in cancer cells by promoting G1-S cell cycle transition and by preventing cancer cell-intrinsic tumor suppression." (PMID 30518851, 2018). "It is a well-established tumor suppressor gene which can form a complex with CDK4 or CDK6 and prevents the activation of the cyclin dependent kinase to inhibit cell cycle progression." (PMID 30266084, 2018). "A potential molecular biomarker for palbociclib response is mutant KRAS status, first suggested through in vitro and in vivo work in tumor cell lines and mice where synthetic lethality was observed following CDK4 inhibition." (PMID 30647837, 2018). "Many studies focusing on the oncogenic functions of c-Fos have demonstrated its involvement in tumor growth through the modulation of Cyclin D1, which is a nuclear regulatory subunit of the cyclin-dependent kinases (CDK)-4 and CDK-6." (PMID 30423928, 2018). "Successful expansion of CDK4/6 therapies will require pre-treatment biomarkers that are predictive of response and are applicable in a large number of diverse tumor types." (PMID 29789718, 2018). "Expression of CDK4 and cyclin D1 was increased in tumor sections with SKA3 overexpression (vs. control vector, **p < 0.01) but decreased in tumor sections with SKA3 knockdown." (PMID 30459531, 2018). "The targeted genotyping panels (T200/T200.1 and FM) detected several other CNAs, in addition to MDM2 and CDK4, and many of them were found in more than one tumor sample." (PMID 29731991, 2018). "Proteins in this cell proliferative pathway include p16, an endogenous suppressor of CDK4/6, cyclin D1, the regulatory subunit of CDK4/6, and retinoblastoma (Rb) protein, a tumor suppressor." (PMID 30322180, 2018). "In treated tumor tissues we also observed decreased protein levels of cyclin D1, CDK4 and CDK6 when compared to control tumors and the IHC staining of cyclin D1 showed reduced intensity in erufosine treated as compared to untreated tumors." (PMID 29464035, 2018). "We will also discuss the relevance to the anti-tumor mechanisms of aspirin, CDK4 inhibitors, and other therapeutic agents." (PMID 30301139, 2018). "As a fundamental cell division modulator, CDK4 functions mainly through activation, by phosphorylation, of the retinoblastoma tumor suppressor, inducing G1 cell cycle arrest in tumor cells." (PMID 29670090, 2018). "CDK4/6i can also induce antitumor immunity by overcoming two tumor immunoevasion mechanisms via (i) presenting tumor surface antigens with enhanced efficiency and (ii) inhibiting immunosuppressive Treg cell proliferation." (PMID 30191140, 2018). "These active cyclin D/CDK4 complexes induce the phosphorylation of Rb, and thereby switch off the tumor suppressing function of Rb13." (PMID 29670090, 2018). "We undertook an analysis of the PALOMA-3 trial to assess the utility of early ctDNA dynamics in predicting outcome on CDK4/6 inhibitors, and to investigate the implications of tumor heterogeneity." (PMID 29497091, 2018). "The CDK4/6 inhibition resulted in potent suppression of tumour growth in the primary tumour explants illustrating the similarities of the biology between primary tumour model and tumour of origin." (PMID 30340359, 2018).
tumor (continued). "We found that NEAT1 inhibition plus DDP in vivo inhibited the BCL-2/caspase-3 levels and increased the BAX expression for tumor apoptosis, and also repressed the cyclin D1/CDK4 expression for cell cycle arrest." (PMID 29654165, 2018). "Regarding cell cycle regulation, the level of CDK4 responsible for retinoblastoma phosphorylation in G1-S transition, increased with ~ 4-fold in both tumor samples." (PMID 29415661, 2018). "Recent pre-clinical and clinical studies have demonstrated the advantage of inhibiting CDK4/6 driven proliferation in advanced ER+ tumours." (PMID 30034634, 2018). "The downregulation of MDM2 following treatment with CDK4/6 inhibitors also induces many cultured tumor cell lines derived from different types of malignancies to progress from quiescence into senescence." (PMID 29789718, 2018). "For example, in our previous study, the anti-tumor effect of CDK4/6 inhibitor SHR6390 was demonstrated in ESCC." (PMID 29370817, 2018). "Remarkably, it was predicted over 2 decades ago that CDK4/6 inhibition would only restrain tumor cell proliferation in samples that retained an intact functional RB gene product." (PMID 30647837, 2018). "Second, we anticipated that combining MEK and CDK4/6 inhibition would enhance tumor cell cytotoxicity in vitro and we studied these combinations in cell lines with either wildtype or mutant RAS." (PMID 30647837, 2018). "Increased CDK4 activity is a common occurrence in cancer and contributes to cancer progression by allowing unrestricted proliferation of tumor cells." (PMID 30301139, 2018). "This cross talk between NF-κB and nucleoli is important for the anti-tumour effects of aspirin and small molecule CDK4 inhibitors, suggesting therapeutic relevance." (PMID 30301139, 2018). "Consistent with inhibition of the G0/G1-S transition, we also measured reduced expression of CDK4 in reprogrammed tumours and reduced RB phosphorylation at Ser780 (the RB amino acid substrate of the Cyclin D1-CDK complex) in reprogrammed tumours." (PMID 29662623, 2018). "There are two general outcomes of CDK4/6 inhibition-induced cell cycle exit in Rb-positive tumor cells." (PMID 29789718, 2018). "The decision of a tumor cell to senesce after CDK4/6 inhibition is made after the cell has withdrawn from the cell cycle." (PMID 29789718, 2018). "The importance of cyclin D holoenzymes for inactivation of Rb and the development of cancer in mice prompted the development of CDK4/6 inhibitors to treat a variety of neoplasms." (PMID 29789718, 2018). "In this review, we will discuss these points of crosstalk and their relevance to anti-tumour mechanism of aspirin and small molecule CDK4 inhibitors." (PMID 30301139, 2018). "It has now been well established that the RB tumor suppressor is a primary target of CDK4 and CDK6 kinases." (PMID 30701029, 2018). "ERMS tumor also harbored additional gene alterations: low amplification of EGFR, PDGFRA, and CDK4 genes, and loss of heterozygosity of CDKN2A and 19q12-19q13.43 chromosomal regions." (PMID 28222777, 2017). "We suggest that patients whose tumor cells have pRB activatable p27 will benefit most from CDK4/6 inhibitors." (PMID 28293272, 2017). "This group contains positive regulators of cell cycle and DNA-damage responses (i.e. Cdk4, Ccne2, and Met), whose suppression bestows anti-tumor functions to miR-34 family miRNAs." (PMID 28241004, 2017). "Targeting CDK4/6 mediated Rb phosphorylation by small molecule inhibitors has the possibility to block cell cycle progression and suppress tumor growth." (PMID 28578693, 2017). "Many acquired gene amplifications were identified in the patient's tumor profile; several of these amplifications were present in the responding tumor (MLCL, CDK4, and KRAS) and are less likely to be associated with resistance." (PMID 28915719, 2017).
tumor (continued). "While the cyclin D/CDK4/6/p16INK4a/RB pathway is frequently disrupted in cancer, the majority of human neoplasms maintain functional RB but have aberrations that increase the activity of CDK4/6, which hyper-phosphorylates RB and allows cell proliferation." (PMID 28418845, 2017). "p21WAF1/CIP1 has been proposed as an alternate tumor suppressor that inhibits cell growth and the RB pathway by blocking CDK4/CDK6 activity and RB phosphorylation through inhibiting cyclin E and CDK4 in neural progenitor cells." (PMID 28968963, 2017). "The increased p21WAF1 expression inhibited cyclin D1/CDK4 complex activity, which explains cell cycle arrest in the G1 phase, and the cell cycle arrest contributed to the 7E-induced inhibition of tumor growth." (PMID 29242565, 2017). "Consistent with earlier work published with palbociclib, the expression of genes induced by the treatment with CDK4/6 inhibitors is more variable across tumor types and models." (PMID 28620137, 2017). "D-type cyclins are overexpressed in various cancer types and several studies are focusing on CDK4/6 inhibition to target these tumours." (PMID 28177473, 2017). "Our report would support the need for randomized phase III clinical studies specifically designed to test the anti-tumour activity of CDK4/6 inhibitors as single agents or in combination in MM on the basis of the molecular characteristics of this tumour." (PMID 28680533, 2017). "Although many first generation non-selective CDK4/6 inhibitors failed in clinical development due to toxicity, current CDK4/6 inhibitors in clinical trials are well-tolerated and have demonstrated potential efficacy in a wide variety of tumor types." (PMID 29245989, 2017). "Preclinical studies have shown that CDK4/6 inhibitors induce G1 arrest of human cancer cell lines, suppressing tumor growth or inducing tumor regression." (PMID 29156680, 2017). "It has been reported that the efficacy of CDK4/6 inhibitors requires functional Rb expressing in tumor cells." (PMID 28578693, 2017). "One of the mechanisms by which p16INK4a inhibits tumor growth under hypoxic conditions is mediated through the interaction of p16INK4a with CDK4 and a subsequent decrease in CDK4 catalytic activity." (PMID 29179500, 2017). "In this respect, the prediction of these three tumor CDK4 modification profiles based on the gene expression profile of 11 genes is a key promising achievement of our work." (PMID 28566333, 2017). "Here, the authors demonstrate that inhibition of cell cycle regulators CDK4/6 or MAPK blockade enhances the efficacy of EGFR inhibitors for these tumours in mice." (PMID 28059068, 2017). "In this review, we will first elaborate the anti-tumor mechanisms of CDK4/6 inhibitors, and then trace the preclinical and clinical evidence of these three highly specific inhibitors." (PMID 28438180, 2017). "We reconstituted CDK4 in Tspan5-overexpressing tumour cells by transfecting the pCMV-Myc-CDK4 construct and confirmed the upregulation of CDK4 in tumour cells by Western blotting." (PMID 27223087, 2016). "To corroborate the role of cyclin D1 and CDK4 in the suppression of tumour growth of GC by Tspan5, we reconstituted the expression of cyclin D1 and CDK4 in Tspan5-overexpressing tumour cells." (PMID 27223087, 2016). "We also showed that HEGU suppresses the orthotopic growth of 4T1 allografts and the expression of proliferating nuclear cell antigen and cycle dependent kinase-4 (CDK-4) proteins in tumor tissues." (PMID 27314329, 2016). "This is based on data showing ErbB2-driven tumor arrest and senescence in vivo in response to acute cyclin D1 ablation or targeted inhibition of CDK4/6." (PMID 26857361, 2016).
tumor (continued). "In unresectable or metastasizing tumor stages CDK4/6 inhibitors (Palbociclib) or PI3K inhibitors (Pazopanib) seem to be promising treatment options." (PMID 26943575, 2016). "These clinical studies showed that inhibition of CDK4/6 kinase activity prevents proliferation and tumor growth." (PMID 27759034, 2016). "We prepared tumor tissue sections and used immunohistochemistry to detect hSulf-1 expression, CDK4 expression and AKT phosphorylation levels." (PMID 27806323, 2016). "In the high glucose condition, PRMT5 was shown to emphatically interact with CDK4, releasing it from CDKN2A and leading the CDK4-RB-E2F axis to an active state for tumor growth." (PMID 27708221, 2016). "Here, we show that the localization of Ccnd1·Cdk4 in the membrane of fibroblasts and tumour cells has an active role in the induction of cell migration and invasion through the phosphorylation of Pxn." (PMID 27181366, 2016). "Cyclin D1 (Ccnd1) together with its binding partner Cdk4 act as a transcriptional regulator to control cell proliferation and migration, and abnormal Ccnd1·Cdk4 expression promotes tumour growth and metastasis." (PMID 27181366, 2016). "The canonical function of CDK4/6 inhibition is to elicit the functional activation of the RB tumor suppressor and block subsequent cell cycle progression." (PMID 27564114, 2016). "CDK4 is an important cell cycle regulator, and the inhibition of CDK4 results in the decreased proliferation of tumour-specific effector T cells." (PMID 27484289, 2016). "Our study also highlights the promising use of CDK4 pharmacological inhibitors as a potential new drugs to eliminate cancer stem cells and further prevent tumor recurrence in human TNBCs." (PMID 27759034, 2016). "One CDK4 amplified tumor with grey-zone MDM2 amplification showed only a low HMGA2 copy number increase." (PMID 27662657, 2016). "Among the pairs of tissues, we found that the expression level of CDK4 was upregulated in tumor tissues, as compared with their adjacent pair-matched non-tumor tissues (P<0.05)." (PMID 27049724, 2016). "pl6 (also known as CDKN2) is a tumor suppressor gene which decelerates cell progression from G1 phase to S phase by inhibiting cyclin dependent kinases such as CDK4 and CDK6." (PMID 27429046, 2016). "Here, we provide considerable evidence of a positive role for PRMT5 and CDK4 in tumor cell cycle regulation." (PMID 27708221, 2016). "Immunohistochemistry results showed that AKT phosphorylation in tumor cells was decreased and that nuclear CDK4 levels were reduced." (PMID 27806323, 2016). "As pRb is a substrate of CDK4/6-cyclin D, palbociclib targets Rb+ tumor cells in vitro, inducing G1 arrest, with concomitant elimination of phospho-Rb and inhibition of E2F-dependent transcription." (PMID 25914884, 2015). "The MPNST-derived S14 PDXs responded to CDK4 inhibition with a clear reduction in tumor growth rate, and we even observed one tumor that disappeared in a mouse that survived." (PMID 26528855, 2015). "Treatment of mice with honokiol resulted in a marked decrease in the expressions of cyclin D1 and cyclin D2 and reduced expressions of Cdk4 and Cdk6 in tumor samples obtained from honokiol-treated mice compared to tumor samples from control mice." (PMID 26020804, 2015). "Tumor cells must contain Rb if CDK4/6 inhibition is to be effective, and the majority of HR+ tumors have intact Rb gene expression." (PMID 27648347, 2015). "The suppression of Nischarin and LKB1 in these cells resulted in increased phosphorylation of PAK1 and LIMK1, and upregulation of Cyclin D1 and CDK4 expression, resulting in enhanced cell migration and tumor growth." (PMID 25695373, 2015). "In the fresh subcutaneous tumor, we detected the expression of miR-1 by RT-PCR and the expression of CDK4, CDK6, Caprin1 and Slug by Western Blot." (PMID 26036633, 2015).
tumor (continued). "Although most breast cancers maintain functional Rb, a variety of other factors can corrupt the CDK4/6-cyclin D pathway, promoting cellular proliferation and tumor growth." (PMID 26726315, 2015). "There are ongoing trials designed to test the utility of CDK4 genomic alterations in predicting the tumor response to CDK inhibitors." (PMID 26528855, 2015). "Our results indicated that protein levels of CDK4 in A549 tumour biopsies were marginally reduced in ACA treated, rhAFP/ACA 1:3 ratio and rhAFP/ACA 1:5 ratio groups compared to other treatment groups." (PMID 26158863, 2015). "Conversely, the second is intended to reactivate RB1 tumor suppressor function, principally through the use of CDK4/6 inhibitors that have shown promise in clinical trials." (PMID 26160835, 2015). "Alternatively, the S11-derived tumors responded to CDK4 inhibition by greatly delaying tumor growth; as a result, the treated mice survived almost twofold longer than the untreated mice." (PMID 26528855, 2015). "Alternatively, the S29-leiomiosarcoma responded initially to the CDK4 inhibitor, but after ending the treatment, tumor growth recovered, and the survival of the treated mice was only slightly longer than that of the untreated controls." (PMID 26528855, 2015). "In fact genetic alterations in components of the pRb/CDK4/cyclin D/p16INK4a pathway are amongst the most frequently occurring anomalies reported, found in more than half of all human tumours." (PMID 25625291, 2015). "Taken together, our findings established a tumor suppressive role for miR-1 in the progression of ccRCC by targeting CDK4, CDK6, Caprin1 and Slug and suggested miR-1 can be served as a novel potential therapeutic target for ccRCC." (PMID 26036633, 2015). "The IHC analysis results revealed that the number of lipid vacuoles and the expression of PCNA, Ki67, CDK2, and CDK4 were significantly greater in tumor tissues obtained from the mice fed on the HFD as compared to those of CD-fed mice." (PMID 25912035, 2015). "In vitro studies show that Mps1 inhibitor cytotoxicities are ameliorated when combined with a cytostatic, selective CDK4/6 drug that pauses the cell cycle progression of normal cells while keeping tumor cells vulnerable to Mps1-mediated cell death." (PMID 26398286, 2015). "NEUROG1 is a transcription factor involved in neuronal development and differentiation, and CDKN2A (p16) is a tumor suppressor that inhibits cyclin-dependent kinases CDK4 and CDK6." (PMID 26157509, 2015). "The future success of trials evaluating CDK4/6 inhibitors in CRPC is likely to hinge on enrichment with patients whose tumours exhibit cyclin/CDK activation in the background of intact RB1." (PMID 25896606, 2015). "Here the authors use C. elegans as a model system to identify downstream regulators that are critical in the response of tumour cells to Cdk4/6 inhibitors." (PMID 25562820, 2015). "Overexpression of CDK4/6 or D-type cyclins and inactivation of the CDK4/6 antagonist p16INK4A/CDKN2A or Rb tumour suppressor are common in human cancer." (PMID 25562820, 2015). "In the present study, the relative expression of mRNA by real-time PCR showed that PSMD10 and CDK4 genes were over-expressed (P = 0.034; P = 0.006) in the tumor tissues of the Cs+NDMA group hamster’s liver." (PMID 26313366, 2015). "In this pathway, proteins of the INK4 and RB families function as tumor suppressors, whereas D-type cyclins, CDK4/6, and E2F promote tumor proliferation." (PMID 26317630, 2015). "In human clinical trials, CDK4 inhibitors (CDK4i) have had some success controlling tumor progression but why some patients respond well and others poorly is not understood." (PMID 25803170, 2015).